MAGEB10 (MAGE family member B10)
Synonyms: FLJ32965
Tractability: PROTAC: ubiquitination databases record sites on it.
Gene: Protein-coding gene on chromosome X (27,807,990 to 27,823,014, forward strand). Ensembl gene ENSG00000177689.
Gene Ontology:
Molecular function: protein binding
Biological process: negative regulation of transcription by RNA polymerase II
Cellular component: nucleus; cytoplasm
Homologues: Orthologues: chimpanzee MAGEB10 (97% identical), macaque MAGEB10 (90% identical), pig MAGEB10 (63% identical), rabbit MAGEB10 (63% identical), guinea pig MAGEB10 (52% identical), zebrafish ndnl2 (22% identical), Drosophila melanogaster MAGE (18% identical). Paralogues in human: MAGEB18 (52% identical), MAGEB4 (51% identical), MAGEB1 (50% identical), MAGEA10 (47% identical), MAGEB17 (46% identical), MAGEB3 (46% identical), MAGEB16 (45% identical), MAGEB2 (45% identical), MAGEB6B (41% identical), MAGEA8 (39% identical), MAGEB6 (39% identical), MAGEA9 (38% identical), and 25 more.
Diseases named in the same sentence as MAGEB10 in open-access papers:
MAGEB10 is named in the same sentence as 5 diseases in open-access papers, as found by Europe PMC text mining. Sharing a sentence is not in itself a finding about the gene and the disease. The quoted sentences say what the papers report.
ovarian carcinoma (1 paper, 2021). A malignant neoplasm originating from the surface ovarian epithelium. "Antibody-profiling serum from healthy controls (n = 35), benign controls (n = 12) and ovarian cancer patients across four disease subtypes (n = 80) using the custom protein array showed detectable autoantibodies (Z-score > 0) against all antigens except CAMKV and MAGEB10 (n = 48/50)." (PMID 34681879, 2021).
MAGEB10 also shares sentences with these, for which no sentence is quoted: carcinosarcoma (1 paper); colorectal cancer (1); epithelial neoplasm (1); mesenchymal neoplasms (1).